ATM (ATM serine/threonine kinase)
Diseases named in the same sentence as ATM in open-access papers (continued):
Sharing a sentence is not in itself a finding about the gene and the disease.
ataxia telangiectasia (continued). "Mutations in ATM that result in the absence of detectable protein cause the childhood disease ataxia telangiectasia (A-T)." (PMID 27259260, 2016). "The dysglycaemic ataxia telangiectasia phenotype suggests that ATM may regulate several processes important in carbohydrate metabolism." (PMID 26606753, 2016). "A predisposition role for ATM in gastric cancer was not known, although some evidence of excess risks was reported from Ataxia-telangiectasia family studies." (PMID 26506520, 2015). "Biallelic inactivation of ATM results in Ataxia-telangiectasia." (PMID 26506520, 2015). "Ataxia-telangiectasia (A-T) is a multisystemic neurodegenerative disease of childhood caused by the absence of functional ATM (A-T mutated) protein." (PMID 26465009, 2015). "To test whether ATM regulated sCLU expression during cellular senescence, we aged human diploid Ataxia telangiectasia (AT) patient fibroblasts that lack functional ATM expression." (PMID 24937130, 2014). "Similar to observations in ATM-inhibited or ataxia-telangiectasia cells exposed to DNA damaging agents, these results suggest that ATR and DNA-PKcs may cross-phosphorylate substrates of ATM during SV40 infection." (PMID 25474690, 2014). "Conversely, Ataxia–Telangiectasia patients carrying P/LP variants within exons 55–63, which are nor part of the mini-ATM structure, may represent a cohort that could benefit from glucocorticoid therapy." (PMID 41596415, 2026). "However, in multiple cases, ATM c.1066-6T>G was identified together with another pathogenic ATM variant that did not have an ataxia telangiectasia phenotype, and some articles state that ATM c.1066-6T>G is benign." (PMID 40507299, 2025). "ATM may also regulate CH through its role in telomere maintenance, as variants in the telomerase reverse transcriptase (TERT) are associated with CH and ATM loss in ataxia telangiectasia leads to telomere shortening." (PMID 39352380, 2024). "Lymphoid neoplasms associated with clinical syndromes are identified separately, including ataxia telangiectasia (AT) and Nijmegen breakage syndrome (NBS) with specific germline mutations in ATM and NBN, respectively." (PMID 38835969, 2024). "Ataxia-telangiectasia (A-T) is an autosomal recessive disorder that results from biallelic mutations in the A-T mutated (ATM) gene, causing ATM deficiency or production of nonfunctional ATM protein." (PMID 37756394, 2023). "Classic ataxia telangiectasia is associated with homozygous mutations of the ATM gene, the complete absence of its kinase activity and/or deleterious ATM gene mutations such as truncation/nonsense mutations, loss of function mutation, non-conservative substitutions, frameshift, and deletions." (PMID 36439585, 2022). "Genetic defects in ATM lead to ataxia telangiectasia (AT) presenting with combined immunodeficiency, genomic instability with predisposition to cancer, severe cellular sensitivity to IR, and cerebellar degeneration." (PMID 34594342, 2021). "In an alternative approach, genes encoding a small number of proteins implicated in DNA repair pathways in other eukaryotes are not apparent in the D. discoideum genome including ATM, a damage-activated protein kinase whose mutation in humans leads to Ataxia Telangiectasia." (PMID 34692705, 2021). "However, functional effects of the ATM mutations are not clear; ataxia telangiectasia (A–T) mutations in ATM are known to induce protein truncation, protein destabilization, and resulting loss of function." (PMID 34201502, 2021). "ATM is involved in the genetic disorder ataxia telangiectasia (AT), which is characterized by cerebellar ataxia, oculocutaneous telangiectasia, immunodeficiency, and a predisposition to cancer." (PMID 32425970, 2020). "These include the clinically similar Ataxia telangiectasia (AT), AT like disease (ATLD), Nijmegen Breakage Syndrome (NBS) and NBS like disorder (NBSLD), caused by mutations in the ATM, MRE11, NBS1 and RAD50 genes respectively." (PMID 26160886, 2015).
ataxia telangiectasia (continued). "The ATM gene was localized to the chromosomal sub-band 11q22-q23 by genetic linkage analysis in families with members affected by ataxia telangiectasia (AT) in 1988." (PMID 17623063, 2007). "Cell lines derived from patients with ataxia-telangiectasia and from engineered ATM knockout human or mouse models are sensitive to DNA-damaging agents and PARP inhibitors, raising the possibility that cancers with a functional loss of ATM could be particularly sensitive to these agents." (PMID 37627223, 2023). "The classification of AT is based on absence of the affected Ataxia Telangiectasia Mutated (ATM) protein and/or its kinase activity: patients without ATM protein or kinase activity present as classic AT with (early) childhood onset." (PMID 34248969, 2021). "MRE11, together with RAD50 and NBS1 (MRE11-RAD50-NBS1 complex), locates to the end of the double-strand breaks (DSBs) locus and activates ATM through the interaction between ATM and NBS1, triggering ataxia telangiectasia and ATR activation." (PMID 34917121, 2021). "While ataxia telangiectasia and C9orf72-ALS share defective ATM signalling, the nature and origin of this defect are fundamentally different." (PMID 29584802, 2018). "Cancer-prone patients suffering from ataxia-telangiectasia exhibit radioresistant DNA synthesis (RDS) and disruption of the ATM-Chk2 pathway results in defective S phase checkpoint and RDS." (PMID 23554659, 2010). "To examine this, we exposed a WT LCL and LCLs derived from an NBS, Ataxia-Telangiectasia (A-T) and DIAL syndrome patient to IR and used Western blotting coupled with phospho-specific antibodies to known ATM substrates to assess ATM activation in response to DNA damage." (PMID 40368919, 2025). "Clinical and in vivo studies reveal a similar pattern: patients with inherited dysfunctional ATM alterations (termed Ataxia-telangiectasia, A-T) and mice lacking Atm function are immunocompromised and have an increased risk of developing lymphomas." (PMID 33066395, 2020). "There is emerging evidence that the phenotype observed in ataxia-telangiectasia is unlikely to be solely related to the nuclear DNA repair functions of ATM and that ATM has a role in the mitochondria." (PMID 31641109, 2019). "Defective ATM signalling provides a molecular link between ALS and ataxia telangiectasia." (PMID 29584802, 2018). "An immortalized cell line from an ataxia telangiectasia individual that expresses no ATM and a similar cell line from a patient that expressed ATM were used as technical controls." (PMID 27259260, 2016). "ATM has been widely studied since individuals with the disease ataxia telangiectasia, who express no ATM protein, are the most radiosensitive patients identified." (PMID 26517239, 2015). "ATM has been widely studied since ataxia telangiectasia individuals who express no ATM protein are the most radiosensitive patients identified." (PMID 26517239, 2015). "The impairment of IR-induced altered nuclear staining of methylated TRF2 was also observed in primary ataxia telangiectasia (AT) fibroblast cells (AT2RO) lacking functional ATM." (PMID 24721747, 2014). "Cells established from NBS patients survive following irradiation, but retain γ-H2AX foci due to a subtle DSBs repair defect, albeit at a lower level compared to Ataxia telangiectasia (AT) lymphocytes (characterized by the absence of the ATM protein)." (PMID 25485873, 2014). "We infected cells from patients with ataxia telangiectasia (A–T) and ataxia telangiectasia-like disorder (A-TLD) that lack functional ATM and Mre11 respectively, and compared them to matched controls in which ATM or Mre11 had been reconstituted." (PMID 21698222, 2011). "It has been recently described that the ATM gene has an important role in iron metabolism, in particular in regulation of ferroptosis; however, clinical correlation of these findings in children with ataxia telangiectasia have not been yet described." (PMID 39917433, 2024).
ataxia telangiectasia (continued). "As a consequence, this will lead to a pathology associated with accumulation of DNA lesions and sensitivity to oxidative stress, and indeed ataxia-telangiectasia patients who have absent or inactive ATM protein display features of neurodegeneration, premature aging or genomic instability." (PMID 23042680, 2012). "Next we determined the contribution of ATM to HCMV replication by assessing viral replication in dermal fibroblasts from a normal donor compared to fibroblasts from a patient with ataxia telangiectasia (AT) that do not express detectable levels of the ATM protein." (PMID 21589897, 2011). "Given these previous case reports of insulin resistance in ataxia telangiectasia, and the novel finding that ATM may influence metformin response, we aimed to investigate glucose metabolism in participants with ataxia telangiectasia in the absence of a diagnosis of diabetes." (PMID 26606753, 2016). "The identification of the role of ATM on ITCH signaling may be relevant as it is tempting to speculate that the alteration of ITCH activity regulation due to the absence of ATM kinase activity may contribute to the Ataxia Telangiectasia pathogenesis." (PMID 25594035, 2014). "Thus, as expected, the initial response to the intoxication is partly ATM-dependent, since a delayed response has been detected in lymphoblastoid cells derived from Ataxia telangiectasia (AT)-patients, carrying a non-functional kinase." (PMID 26270677, 2015).
prostate carcinoma (239 papers, 2004 to 2026). A carcinoma that arises from epithelial cells of the prostate gland. "Heterozygous carriers of ATM pathogenic variants have been found to be at increased risk for breast, pancreatic, and prostate cancers and more recently there have been suggested associations with ovarian cancer and some reports of lymphoid malignancies." (PMID 41495781, 2026). "Although the PARP inhibitor olaparib is approved for ATM‐mutated ovarian and prostate cancers, its effectiveness in lung cancer remains largely unexplored." (PMID 40622001, 2025). "For individuals with a GPV in CHEK2 or ATM, we provide best practice guidance which favours providing information regarding prostate cancer risk at a results appointment with patient-initiated follow-up (PIFU) if and when required." (PMID 41159931, 2025). "For example, in prostate cancer, pathogenic germline variants in DNA repair genes (ATM, CHEK2, PALB2, BRCA2) vary by ancestry; some are enriched or even unique to specific populations, leading to differences in prevalence and risk across groups." (PMID 41573212, 2025). "A loss of the ATM protein through genetic mutations has been found in prostate cancer, with the loss resulting in genomic instability." (PMID 40699691, 2025). "ATM loss-of-function mutations, found in 5–7% of advanced prostate cancers, and constitutive ATR activation further enhance checkpoint responses, enabling evasion of mitotic catastrophe." (PMID 40725389, 2025). "Men with BRCA2-mutated or ATM-mutated prostate cancer have an increased risk of developing aggressive disease and show relatively poor prognosis." (PMID 40046829, 2025). "Case 4 presents a 74-year-old male with extensive metastatic disease who initially responded to the treatment but later exhibited disease advancement and an ATM gene mutation, signaling a shift to metastatic castration-resistant prostate cancer (mCRPC)." (PMID 38577344, 2024). "As a monotherapy, ATR inhibitors have demonstrated synergistic efficacy in ATM-deficient prostate cancer models." (PMID 38672592, 2024). "In mCRPC, ATM mutations are present in 5-8%, while the prevalence is two-fold lower in primary prostate cancer." (PMID 39172235, 2024). "For example, while olaparib has been FDA‐approved for metastatic CHEK2‐ and ATM‐mutated prostate cancer; therapeutic benefit in these patients was suboptimal in comparison to patients harboring BRCA1/2 mutations." (PMID 38898688, 2024). "For prostate cancer, the ATM gene which is involved in DNA repair has been associated with an increased risk of developing prostate cancer." (PMID 39796639, 2024). "Clinically actionable opportunities associated with PRMT5 regulation of DDR genes have been largely unexplored, although several studies have indicated susceptibility of blood and prostate cancers to ATM inhibitors or irradiation." (PMID 37861290, 2023). "Germline alterations in several HRR genes, such as BRCA, ATM and others, are associated with increased prostate cancer risk, and are generally associated with worse prognosis for patients with prostate cancer." (PMID 37434977, 2023). "WES analysis of the cohort revealed 38 different variants, including a variant (rs1800057, ATM:c.3161C>G, p.P1054R) associated with prostate cancer that had a higher frequency in our cohort." (PMID 38327652, 2023). "The estimated HR for prostate cancer associated with ATM mutations was 3.5 (p = 0.11, 95% CI 0.69–18.2)." (PMID 35892882, 2022). "BRCA1/BRCA2/ATM mutations were the first reported molecular alterations conferring sensitivity to PARP inhibitors in prostate cancer and are the most widely studied germline and somatic mutations in this setting." (PMID 35448200, 2022). "The importance of these genes to HRR likely vary, where ATM deficiencies appear less important than BRCA1/2 in prostate cancer, given the lower response rate to PARPi for ATM-deficient tumors." (PMID 35681599, 2022).
prostate carcinoma (continued). "A study of prostate cancer patients with heterozygous ATM mutations found an increased risk of late complications of external beam radiotherapy." (PMID 35732815, 2022). "BRCA1/2 and ATM aberrations have been reported to be associated with a more aggressive prostate cancer phenotype, with an increased risk of disease recurrence and poorer survival outcomes." (PMID 35740343, 2022). "The final cohort comprised 15 confirmed germline mutation carriers with prostate cancer (ATM n = 9, CHEK2 n = 2, HOXB13G84 n = 4)." (PMID 35892882, 2022). "Initial trials using olaparib, a PARP inhibitor, for treatment of metastatic, castration-resistant prostate cancer showed an impressive response rate among patients with PVs in the HR repair pathway, including patients with ATM deficiency." (PMID 35008949, 2022). "In a larger series with longer follow-up, men with BRCA 1/2 or ATM mutations were more likely to harbor aggressive prostate cancer." (PMID 35205755, 2022). "We identified ancestry-linked germline and somatic mutation frequencies in DNA damage repair genes (BRCA1, BRCA2, APC, and ATM), as well as three novel prostate cancer–associated genes (CACNA2D2, SYNE1, and ADAMTS2)." (PMID 36922933, 2022). "Early work on the relationship between ATM mutations and prostate cancer found that there was a strong association between late complications of external beam radiotherapy and mutations of this gene." (PMID 35205755, 2022). "An ongoing basket phase II study (NCT03682289) is currently evaluating the combination of ceralasertib and olaparib in multiple tumour types, including prostate cancer; this trial includes a subgroup of 20 patients with ATM loss (10 with mCRPC)." (PMID 36497408, 2022). "Given the relatively high prevalence of ATM mutations in prostate cancer, we decided to generate an additional ATM KO cell line in another prostate cancer cell line, LNCAP, which also resulted in increased sensitivity to olaparib treatment." (PMID 36969741, 2022). "Testing criteria for therapeutically significant somatic and/or germline mutations such as ATM has been recommended following evidence that ATM pathogenic mutations are associated with efficacy of gene-targeted therapies and early age of prostate cancer onset." (PMID 35892882, 2022). "Compared to other solid tumor cell types we have previously tested, the activation of ATM caused by GZ17-6.02 was significantly greater in prostate cancer cells." (PMID 36408163, 2022). "Yadav and colleagues observed increased somatic mutations of BRCA2, BRCA1, and ATM in AA prostate cancer." (PMID 36922933, 2022). "We found associations between the known prostate cancer gene ATM and any 2+ primary cancers and in our prostate cancer-specific analysis (pLOF + missense, p = 9.84 × 10−7 and 2.56 × 10−6)." (PMID 36199081, 2022). "A decreased expression level of ATM was associated with inferior OS and higher prostate cancer-specific mortalities." (PMID 35270630, 2022). "Germline ATR and ATM were associated with higher HRD in BRCA (FDR < 8.5 × 10−8), and germline ATM variants in prostate cancer (PRAD, FDR = 9.0 × 10−6), lung adenocarcinoma (LUAD, FDR = 5.8 × 10−5), and STAD (FDR = 0.007)." (PMID 34572800, 2021). "The loss of ATM occurs in prostate cancer and was recently suggested to increase cell sensitivity to ATR inhibition." (PMID 34977872, 2021). "In prostate cancer, targeted next-generation sequencing has revealed an 8% incidence of ATM mutations." (PMID 34068084, 2021). "In advanced prostate cancer patients with BRCA1/2 or ATM mutations, poly (ADP-ribose) polymerase inhibition (PARPi) causes an increased overall survival advantage compared with patients without these mutations." (PMID 34712892, 2021). "Eleven genes previously associated with increased risk of prostate cancer (including ATM, BRCA2, and HOXB13) were identified along with ten new candidate genes." (PMID 33804961, 2021).